MERTK (MER proto-oncogene, tyrosine kinase)
Diseases named in the same sentence as MERTK in open-access papers (continued):
Sharing a sentence is not in itself a finding about the gene and the disease.
glioblastoma (continued). "We have found that Foretinib, a RTK inhibitor currently in clinical trial, inhibited phosphorylation of TAM receptors, with highest efficacy against MerTK, and blocked downstream activation of Akt and Erk in adult and pediatric glioblastoma cell lines, findings that are previously unreported." (PMID 24658326, 2014). "Our findings provide additional target validation for MerTK inhibition in glioblastoma and demonstrate that robust MerTK inhibition can be achieved with the multi-kinase inhibitor Foretinib as an innovative and translational therapeutic approach to glioblastoma." (PMID 24658326, 2014). "Furthermore, a treatment with the small molecule inhibitor UNC2025 of MerTK led to apoptosis in glioblastoma cell lines indicating that Mer inhibition alone may be of therapeutic value in solid tumors." (PMID 38545840, 2024). "MER receptor tyrosine kinase (MERTK) is expressed in a variety of malignancies, including glioblastoma multiforme (GBM)." (PMID 27783662, 2016). "While comparisons are frequently made between PMT and EMT, the naming of the mesenchymal glioblastoma subtype was based largely on the two markers CD44 and MERTK, with the latter being an unconventional mesenchymal marker." (PMID 38337036, 2024). "It has been shown that MERTK was upregulated in glioblastoma multiforme (GBM)." (PMID 33562150, 2021). "In this regard, macrophages in human glioblastoma highly expressed MerTK while UNC20205, the MerTK inhibitor treatment declined M2 macrophage population in glioma associated microenvironment." (PMID 29455663, 2018). "We and others previously demonstrated co-expression of MERTK and AXL, MERTK and GAS6 (a TAM kinase ligand), and AXL and GAS6 in tumor biopsies from pediatric patients with glioblastoma multiforme." (PMID 27783662, 2016). "The co-culture of apoptotic LN-229 increased the CD40+ GFP+ cell population to ~10% in the parental, SIRPα-negative and MERTK-negative cells, showing that microglial phagocytosis was more efficient on apoptotic glioblastoma cells." (PMID 37483607, 2023). "Axl and MerTK exhibit little to no expression in normal brain but are highly expressed in glioblastoma and contribute to the critical malignant phenotypes of survival, chemosensitivity and migration." (PMID 24658326, 2014). "MerTK activates the STAT3/KRAS and SRC signaling cascades in glioblastoma multiforme (GBM)." (PMID 41195524, 2025). "We identify AXL as the top hit in a CRISPR/Cas9 genome-wide screen in human glioblastoma cells and establish a definitive role of AXL, but not TYRO3 or MerTK, for ZIKV infection." (PMID 40062839, 2025). "Interestingly, there is little to no expression of either Axl or MerTK in normal CNS tissues, making targeting TAM RTKs an attractive novel therapeutic strategy for glioblastoma." (PMID 24658326, 2014).
leukemia (21 papers, 2016 to 2026). A malignant (clonal) hematologic disorder, involving hematopoietic stem cells and characterized by the presence of primitive or atypical myeloid or lymphoid cells in the bone marrow and the blood. "We found that inhibition of MerTK decreased leukemia-associated macrophage expression of M2 markers PD-L1, PD-L2, Tim-3, CD163 and Arginase-1 compared to vehicle-treated controls." (PMID 36960055, 2023). "MRX-2843 is a first-in-class MERTK-selective inhibitor that is currently being tested alone and in combination with other agents in multiple phase I solid tumor and leukemia clinical trials, including a trial in adolescents and young adults." (PMID 39199601, 2024). "Studies have demonstrated that these compounds inhibit MERTK phosphorylation and have a variety of functional effects in in vitro cell-based assays and in vivo models of solid tumors and/or leukemia." (PMID 39062902, 2024). "We previously reported that in leukemia cells, MerTK inhibition using short-hairpin RNA and MerTKIs decreased STAT6 phosphorylation." (PMID 36960055, 2023). "Collectively, these results demonstrated that MerTK inhibition of LAMs was sufficient to improve leukemia-free survival in vivo." (PMID 36960055, 2023). "To assess the downstream effects that LAM MerTK inhibition had on T cell function in the leukemia microenvironment, we assessed checkpoint receptor expression predictive of T cell hypofunction and/or exhaustion." (PMID 36960055, 2023). "MRX-2843 inhibited MERTK activation at a lower IC50 than was required to mediate functional anti-leukemia effects, though these findings are consistent with what we have previously observed in B-ALL and AML." (PMID 36551626, 2022). "In this study, we utilized MRX-2843—a dual MERTK/FLT3 inhibitor currently in clinical trials—to probe the anti-leukemia effects of MERTK inhibition in ETP-ALL and T-ALL models." (PMID 36551626, 2022). "In this study, we have demonstrated that MERTK inhibition mediates direct anti-leukemia effects in MERTK-expressing T-ALL and ETP-ALL models." (PMID 36551626, 2022). "We have shown that MRX-2843 can mediate anti-leukemia effects through inhibition of both MERTK and FLT3 in AML models." (PMID 36551626, 2022). "Oppositely, FTO upregulation in leukemia showed more TKI tolerance via enhancing MERTK and BCL-2 stability." (PMID 34745970, 2021). "In both DSRCT cell lines, the IC50 of UNC2025 was around 104 nM, in line with a previous study of UNC2025-mediated MERTK inhibition in leukemia." (PMID 34885181, 2021). "In pharmacologic point of views, this agent has demonstrated a potent anti-MerTK effect, particularly in a human leukemia cell line (IC50 of 1.1 nM), and a somewhat lower effect in human solid cancer cell lines (around 300 nM)." (PMID 29228560, 2017). "The bone marrow microenvironment contributes significantly to progression of MM and given the implications of MERTK inhibition in other leukemias such as AML and ALL, researchers sought to determine its role in MM." (PMID 27834816, 2016). "Here, we found that MRX2843 treatment similarly decreased STAT6 phosphorylation in leukemia-exposed macrophages, providing a plausible mechanism by which MerTK inhibition leads to macrophage repolarization from cancer-promoting toward a classically activated phenotype." (PMID 36960055, 2023). "The resultant altered leukemia microenvironment led to activation of T cells, which lack MerTK." (PMID 36960055, 2023). "While beyond the scope of this project, we hypothesize that MERTK plays a similar role in the leukemia microenvironment in T-ALL." (PMID 36551626, 2022). "Not only solid cancers, but also leukemias express Axl and MerTK." (PMID 33801886, 2021). "Finally, as TYRO3, AXL, and MERTK are attractive therapeutic targets in leukemia, we will discuss recent advances toward introduction of small molecule inhibitors of MERTK and AXL into the clinic." (PMID 27834816, 2016).
leukemia (continued). "Additionally, it mediates near complete inhibition of MERTK phosphorylation in the bone marrow of leukemia-bearing mice." (PMID 27834816, 2016). "Finally the roles of both AXL and MERTK in leukemia have been well described, but less is known about TYRO3." (PMID 27834816, 2016). "Therefore, targeting efferocytosis through MerTK may help reverse immunosuppression in the leukemia microenvironment." (PMID 36960055, 2023). "To assess whether the prolonged survival observed with MerTK inhibition in the leukemia microenvironment is dependent on T cell function, we performed survival studies in leukemic mice that lack the T cell receptor alpha chain (TCRα-/-) rendering them deficient in α/β T cells." (PMID 36960055, 2023). "Given that LAMs express the prototypic efferocytic receptor MerTK, we sought to evaluate whether targeting MerTK-dependent efferocytosis by LAMs would diminish leukemia growth through skewing of the leukemia microenvironment using a novel clinical grade small molecule tyrosine kinase, MRX2843." (PMID 36960055, 2023). "Thus, targeting LAM-associated MerTK, using MRX2843 could have a novel use: repolarizing the leukemia microenvironment through blocking efferocytosis." (PMID 36960055, 2023). "Based on our previous leukemia cell line data demonstrating a correlation between STAT6 and MerTK phosphorylation, we assessed protein lysates from bone marrow derived macrophages (BMDMs) cultured with (or without) AML cells by immunoblot." (PMID 36960055, 2023). "In primary leukemia, FTO increases the stability of a series of proliferation and survival mRNAs, for example B-cell lymphoma-2 (BCL-2) and tyrosine-protein kinase Mer (MERTK), and subsequently promotes protein synthesis." (PMID 37055798, 2023). "Inhibition of MERTK in B-ALL prevented ERK1/2 activation, increased the sensitivity of B-ALL cells to cytotoxic agents, promoted apoptosis, and delayed disease onset in a mouse model of leukemia." (PMID 39062902, 2024). "Since MerTK is the prototypic efferocytosis receptor, we assessed whether the MerTK inhibitor MRX2843, which is currently in clinical trials, would reverse immune evasion and enhance immune-mediated clearance of leukemia cells." (PMID 36960055, 2023). "Therefore, MERTK serves as a dual therapeutic target in ALL, mediating both direct anti-leukemia effects and anti-leukemia immunity in the bone marrow microenvironment." (PMID 36551626, 2022). "Similar to our results, in leukemia cells, activation of MERTK led to increased pERK expression without altering proliferation." (PMID 27081701, 2016). "Importantly, anti-leukemia effects were abrogated in immunocompromised mice and the leukemia cells did not express MERTK themselves, indicating that the therapeutic activity was caused by immune-mediated effects and not direct leukemia cell killing." (PMID 39062902, 2024). "To evaluate MerTK inhibition on leukemia-associated macrophages (LAMs) in vivo without the confounding factor of cell intrinsic effects, we utilized murine AML cell lines and primary murine AML which had very little or no MerTK expression compared to splenic macrophages." (PMID 36960055, 2023).
acute lymphoblastic leukemia (18 papers, 2016 to 2025). Leukemia with an acute onset, characterized by the presence of lymphoblasts in the bone marrow and the peripheral blood. "The role of MERTK in the development of lymphoblastic leukemia/lymphoma was experimentally tested by constructing a transgenic mouse model that expressed MERTK ectopically in lymphocytes and thymocytes." (PMID 39062902, 2024). "The overexpression of MERTK resulted in the activation of pathways that prevent cell death, leading to lymphoblastic leukemia/lymphoma in 60% of the MERTK transgenic mice, with hematopoietic expression driven by VAV promoter." (PMID 39062902, 2024). "MERTK and AXL have been implicated in numerous hematopoietic malignancies, including acute leukemias (AML and acute lymphoblastic leukemia—ALL), chronic leukemias (chronic myeloid leukemia—CML and chronic lymphocytic leukemia—CLL), and multiple myeloma (MM)." (PMID 27834816, 2016). "In contrast, MERTK kinase seems to be more abundantly expressed in acute lymphoblastic leukaemias, therefore a selective MERTK inhibition could be an interesting therapeutic strategy in this context." (PMID 35626092, 2022). "A previous study using acute lymphoblastic leukaemia cell lines found that prolonged GAS6 exposure for over 18 h led to preferential expression of a lower molecular weight partially glycosylated form of MERTK compared to control samples where the fully glycosylated form was predominant." (PMID 37958886, 2023). "Ectopic expression of MERTK was first noted in acute lymphoblastic leukemia (ALL) and is present in 30–50% of pediatric B-ALL and T-ALL patient samples." (PMID 36551626, 2022). "Within the hematopoietic malignant tumors, ectopic expression of MerTK has been reported in pre-B cell acute lymphoblastic leukemia (B-ALL), T cell acute lymphoblastic leukemia (T-ALL), and acute myeloid leukemia (AML)." (PMID 29554921, 2018). "UNC2025, a small-molecule inhibitor of the MERTK/FLT3 pathway, has demonstrated important antitumor activity against acute lymphoblastic leukemia and acute myeloid leukemia." (PMID 40862051, 2025). "In acute lymphoblastic leukemia, prolonged GAS6 exposure to MERTK led to the production of a partially N-glycosylated form of MERTK, altering its localization within the nuclear-soluble and chromatin bound fractions." (PMID 39062902, 2024). "MERTK was cloned from a B ALL cell line cDNA library and is ectopically expressed in over 30–50% of childhood acute lymphoblastic leukemia samples and the majority of lymphoid leukemia cell lines, but was not expressed in normal T and B lymphocytes." (PMID 34830794, 2021). "MerTK was first identified on a B lymphoblast library, and later characterization of acute myeloid leukemia (AML) and acute lymphocytic leukemia (ALL) showed expression in more than 80% of patient samples." (PMID 33801886, 2021). "However, in a model of acute lymphoblastic leukemia (ALL), the inhibition of MERTK decreased tumor burden and prolonged survival." (PMID 38573347, 2024). "For example, MerTK is abnormally expressed in B and T cell acute lymphoblastic leukemia (ALL), but not expressed in normal mouse and human T and B lymphocytes in any stage of development." (PMID 33114206, 2020).
liver fibrosis (18 papers, 2015 to 2025). "Human genetic studies have shown that two single-nucleotide intronic polymorphisms in MerTK, rs4374383 A and rs6726639 A, are linked to reduced hepatic expression of MerTK and decreased risk of liver fibrosis." (PMID 40224489, 2025). "The MERTK rs4374383 AA genotype is associated with the lower intrahepatic expression of MERTK and is protective against F2-F4 liver fibrosis progression in MASLD patients." (PMID 40507973, 2025). "In a study, the Rs6726639A variant, reported to be associated with lower hepatic expression of MERTK, was also associated with a reduced risk of liver fibrosis." (PMID 39201329, 2024). "Human genetic studies have shown that hypomorphic variations in the gene encoding c-mer tyrosine kinase (MERTK) protect against liver fibrosis." (PMID 36572816, 2023). "We conclude that HIV/cART-induced liver fibrosis is associated with an accumulation of M2-like (CD68+/MerTK+) macrophages and with activation of IFN-I signaling in the liver of hu-mice." (PMID 35639478, 2022). "MerTK SNPs rs4374383 GG/AG correlate with higher risk and severity of liver fibrosis compared to patients harboring the rs4374383 AA genotype, indicating either pro-fibrotic or hepatoprotective functions, respectively." (PMID 34771611, 2021). "Development and progression of liver fibrosis in HCV-infected patients correlate with a single nucleotide polymorphism (SNP) in the MerTK locus (rs4374383) based on genome-wide association study data." (PMID 34771611, 2021). "Here we evaluated the association between the MERTK rs4374383 single nucleotide polymorphism (SNP) and liver fibrosis progression in hepatitis C virus (HCV)-infected patients." (PMID 30477195, 2018). "In the current study, we evaluated the association between the MERTK rs4374383 SNP and the progression of liver fibrosis in HCV-infected patients via a longitudinal study." (PMID 30477195, 2018). "The preferential binding of IRF1 to the A allele compared to the C allele would downregulate MERTK in patients carrying the A allele, protecting against liver fibrosis and hepatocarcinoma." (PMID 30477195, 2018). "Our study has important advantages in design compared to previous articles that studied the association between MERTK rs4374383 SNPs and progression of liver fibrosis." (PMID 30477195, 2018). "The variant rs4374383, located in MERTK, has been previously associated with hepatic fibrosis in chronic liver conditions, and its contribution seems to be through the modulation of adipokines, cytokines and circulating mononuclear cells activation in response to fat consumption." (PMID 34899679, 2021). "The G allele of the MERTK rs4374383 SNP has been related to liver fibrosis severity in CHC." (PMID 30477195, 2018). "In conclusion, MERTK rs4374383 A carriers had a lower risk of liver fibrosis progression than G carriers, supporting the hypothesis that this SNP seems to possess a critical role in the pathogenesis of liver disease in HCV-infected patients." (PMID 30477195, 2018). "Additionally, deficiency in growth arrest-specific 6 (GAS6), a ligand of MERTK, attenuates hepatic steatosis, inflammation, and liver fibrosis in mouse models." (PMID 30477195, 2018). "Although MerTK-targeting in experimental MASH models has demonstrated to reduce liver fibrosis, MerTK was also shown to confer hepatocyte protection against lipotoxicity through Gas6." (PMID 38298195, 2024). "Studies using NASH mouse models have shown that ADAM17-mediated MERTK cleavage in liver macrophages decreases during the steatosis to NASH transition and MERTK activation promotes, whereas its inactivation suppresses, liver fibrosis." (PMID 36572816, 2023). "Clinical studies support a dichotomic function of MerTK regarding liver fibrosis, as SNP rs4374383 (within MerTK) influences fibrosis in NAFLD patients and those suffering from HCV infection." (PMID 34771611, 2021).